DLC1 (DLC1 Rho GTPase activating protein)
Diseases named in the same sentence as DLC1 in open-access papers (continued):
Sharing a sentence is not in itself a finding about the gene and the disease.
tumor (continued). "And the lower expression of DLC-1 was correlated negatively with tumor differentiation and TNM stage." (PMID 26846339, 2016). "The interaction between talin and DLC1 plays a key role in recruiting DLC1 to FAs and contributes to the tumor-suppressor activity of DLC1." (PMID 27265849, 2016). "DLC1 is well described as a tumor suppressor that prevents cell migration, invasion and metastatic progression in various cancer types." (PMID 27614886, 2016). "This isoform is functional GAP protein and tumor suppressor and targeting of its expression results in the increase of DLC1 related cell processes: RHO activation and cell migration." (PMID 27614886, 2016). "The Dlc1 gene has been found frequently deleted and epigenetically silenced in a variety of human cancers and this has led to the assertion that Dlc1 is a tumour suppressor gene." (PMID 26977077, 2016). "These analyses lead us to conclude that down-regulation of DLC1 often makes a greater contribution to the tumor phenotype than that of DLC2 or DLC3." (PMID 27174913, 2016). "DLC1 maps to the 8p21.3-22 chromosome region, which is frequently deleted in a number of human tumor types." (PMID 27174913, 2016). "The Deleted in liver cancer 1 (Dlc1) gene codes for a Rho GTPase-activating protein that also acts as a tumour suppressor gene." (PMID 26977077, 2016). "It has been reported that DLC1 isoform 1 is less efficient in exerting its tumor-suppressive activity compared with DLC1 isoform 2, which lacks the N-terminal region." (PMID 26095787, 2015). "DLC-1 was identified and selected for further analysis, as it is a metastasis-suppressor gene which is down-regulated in several tumor types." (PMID 26223867, 2015). "DLC-1 is known for its tumor and metastasis suppressive role in cancer by primarily regulating the actin cytoskeleton organization, formation of actin fibres and focal adhesions." (PMID 26260454, 2015). "It was previously reported that HCV replication correlates with miR-141-mediated post-transcriptional silencing of the DLC-1 tumor suppressor." (PMID 25075209, 2014). "According to the observations, DLC1 is often lost in cancer cells; however, it can remain within the stromal component of tumor sections." (PMID 25013499, 2014). "The DLC1 immunoreactivity was particularly noticeable within the capsules surrounding the tumor masses." (PMID 25013499, 2014). "These include caveolin 1 [which directly binds DLC1 and contributes to its tumor suppressive roles], CDKN1B [which is an inhibitor of and directly binds to CDK6], and cyclin D1 [which forms a complex with CDK6]." (PMID 25425654, 2014). "It was previously reported that PNT occurred in 10% of tumor cells after transfection with DLC1 isoform 2 and was accompanied by morphological changes, and then these cells progressed to apoptosis stage." (PMID 24587289, 2014). "DLC1, Deleted in Liver Cancer-1, is a tumor suppressor that is inactivated by genomic deletions or DNA methylation in many human malignancies, including liver, lung, breast, colorectal, and prostate cancer." (PMID 25425654, 2014). "In the remaining tumor samples, DLC1 was observed as a weak or moderate staining of the cytoplasm of the cancer cells." (PMID 25013499, 2014). "It has been demonstrated for the first time, to the best of our knowledge, that the DLC1 protein, although lost in cancer cells, can be present in the tumor microenvironment, which is particularly visible in the FL variant of HCC." (PMID 25013499, 2014). "By contrast, in stromal components, and particularly in the tumor capsules surrounding the tumor masses, a strong DLC1 immunoreactivity was observed in virtually all of the examined samples." (PMID 25013499, 2014).
tumor (continued). "The DLC1 intronic SNP rs561681 is found to fit a recessive model, complying with the tumor suppressive role of DLC1." (PMID 25425654, 2014). "The aim of the present study was to determine the presence and tissue/cellular localization of the DLC1 protein in HCC tumor samples." (PMID 25013499, 2014). "Other diverse tumor suppressive roles of DLC1 include mediation of caspase-3-dependent apoptosis in HCC model, inhibition of VEGF-dependent angiogenesis in prostate cancer model, and suppression of clonogenicity in several types of cancers." (PMID 23826380, 2013). "Similar to Cav1, DLC1 is a tumor suppressor silenced or deleted in many human cancer entities including GC, e.g. by gene methylation." (PMID 23592983, 2013). "DLC1 is a potential tumor suppressor gene, as its expression reduces the migratory capacity of tumor cells." (PMID 24265769, 2013). "Moreover, aberrant methylation of CpG islands in the promoter region of DLC-1 is a common mechanism leading to the transcriptional silencing, suggesting DLC-1 methylation is associated with the downregulation of this gene in CRC and DLC-1 may be a potential tumor suppressor gene." (PMID 23509688, 2013). "In vitro studies have shown that transfection of the Dlc1 gene can inhibit cell growth, abolish in vivo tumour formation and induce apoptosis." (PMID 22792269, 2012). "The usual mechanisms for down regulation of Dlc1 protein in tumours is either deletion of the Dlc1 locus or hypermethylation of the Dlc1 promoter." (PMID 22792269, 2012). "Another recent work showed that Deleted in liver cancer 1 (DLC1), a Rho GTPase-activating protein, is a substrate for phosphorylation by Akt, and this phosphorylation negatively regulates the tumor suppressor function of DLC1 in liver." (PMID 22973521, 2012). "In order to understand the mechanism for reduced Dlc1 protein expression in tumour cell lines, we have studied the methylation status of Dlc1 isoform 2 and 3 promoters by bisulfite treatment of DNA followed by PCR and pyrosequencing." (PMID 22792269, 2012). "We also detected DLC1 interactions with p120RasGAP, α-catenin, and S100A10 proteins in human cells, and assessed their influence on DLC1’s tumor suppressor function." (PMID 22580498, 2012). "Subsequent studies with prostate cancer showed that tumor cells acquire sensitivity to DLC1-induced apoptosis after treatment with HA14-1, a Bcl-2 inhibitor." (PMID 22580498, 2012). "DLC1 meets the criteria for a gatekeeper gene because of its inhibitory effect on tumor cell growth and cell death." (PMID 22580498, 2012). "Like CLDN7, DLC1 is has been considered a tumor suppressor gene involved in the regulation of the actin cytoskeleton, cell polarity, inter-cell focal adhesion, cell migration, and apoptosis through negative regulation of Rho signaling pathways." (PMID 22616718, 2012). "In recent years, DLC1 has emerged as a major tumor suppressor gene and a strong candidate metastasis suppressor gene in HCC and other cancers." (PMID 22580498, 2012). "In HCC cells, a combined treatment involving suberoylanilide hydroxamic acid, a powerful HDAC inhibitor already used in clinical trials, and DLC1 transduction had a synergistic inhibitory effect on tumor cell proliferation and anchorage-independent growth." (PMID 22580498, 2012). "Similar miRNA-based approaches were recently used to functionally validate DLC-1 as a tumor suppressor included in 8p, a chromosomal region that is found deleted in up to 50% of human HCC." (PMID 22792474, 2012). "In summary, the role of DLC1 is rather complex, and, as recognized by others, intricacies of the DLC1 tumor suppressor function and its modulation by multiple and elaborate interactions should stimulate interest and new research in this TSG." (PMID 22580498, 2012).
tumor (continued). "Such was the case with the tensin family of focal adhesion proteins, which serve as a link between the actin cytoskeleton and the cytoplasmic tails of integrins, whose relationship with DLC1 has been thoroughly investigated in different types of tumor cells." (PMID 22580498, 2012). "The methylation of the same genes was also associated with tumor stage RUNX3 (p = 0.040), SCGB3A1 (p = 0.032), SFRP4 (p = 0.033), and DLC1 (p = 0.035)." (PMID 20849603, 2010). "The canine DLC1 is constructed highly similarly to the human gene, which has been shown to be an important tumor suppressor in many forms of cancer." (PMID 19912643, 2009). "Overall DLC1, the most well characterised tumour suppressor candidate in 8p22, was only affected in a single cell line by a copy number decrease that included two other genes." (PMID 18840272, 2008). "Another tumour suppressor gene DLC-1, locating at the human chromosome region 8p22, is frequently deleted in NPC." (PMID 17199893, 2007). "Many tumor suppressorcandidate genes such as CACNA2D2, DLC1, FUS1, H37, HYAL1, RASSF1A, SEMA3B, andSEMA3F and tumor susceptibility genes such as hMLH1 have been isolated from theregion." (PMID 18288251, 2007). "However, the combined inhibition of AKT inhibition (AKTi) + SRC inhibition (SRCi; by mk-2206 and saracatinib, respectively) can inhibit these phosphorylation activities and reactivate the tumor suppressor activity of DLC1 stabilized by EZH2i4." (PMID 39528835, 2024). "DLC1 is considered a tumor suppressor gene in various human cancers." (PMID 38271973, 2024). "Those indicate DLC1 is one of the most essential tumor suppressors on 8p22." (PMID 37737712, 2023). "The ability of Tensin to promote tumour progression is directly correlated with DLC1 expression." (PMID 37296531, 2023). "Tensin proteins commonly interact with the tumour suppressor, DLC1." (PMID 37296531, 2023). "However, it is unclear how and to what extent functional inactivation of DLC1 is achieved by degradation in other tumor entities." (PMID 35322810, 2022). "DLC1 positivity inversely correlated with tumour progression in patients." (PMID 35963849, 2022). "Concomitantly, the high-expression DLC1 group was enriched in tumor immune-related activities." (PMID 35223504, 2022). "The expression of DLC1 was consistently downregulated in tumor samples." (PMID 35223504, 2022). "In addition, circZKSCAN1 was shown to modulate tumor-suppressive properties by sponging miR-873-5p, miRNA that targets DLC1, another tumor suppressor in hepatocellular carcinoma." (PMID 35205610, 2022). "DLC-1 is a negative regulator of tumor formation and plays a role in cell migration." (PMID 36358270, 2022). "DLC1 is often silenced in human cancers and is promising to suppress tumor development in ESCC." (PMID 35414117, 2022). "CIBERSORT was used to assess the relationship between DLC1 and tumor immune infiltration." (PMID 35223504, 2022). "The target gene validation confirmed that DLC1 expression was downregulated in tumor samples." (PMID 35223504, 2022). "The tumor immunity- and inflammation-related activities were mainly enriched in the high-DLC1 expression group, while metabolic pathways were enriched in the low-DLC1 expression group." (PMID 35223504, 2022). "Therefore, these target genes can also provide new directions for future tumor treatment, especially the five genes DLC1, LRFN5, NOVA1, POU3F2 and PRICKLE2 which were positively related to the overall survival time." (PMID 35578189, 2022). "In conclusion, upregulated miR-200c-3p expression in both early and late stage of HGSC could downregulate DLC1, as a tumor suppressor." (PMID 34071861, 2021). "CENPM was highly expressed in tumor tissues, while DLC-1 was significantly downregulated in HCC." (PMID 33591950, 2021).
tumor (continued). "In addition, treatment with a CUL-4A inhibitor or a proteasome inhibitor can substitute functionally for EZH2 inhibition both in increasing the steady-state level of DLC1 protein and in cooperating with the two kinase inhibitors for tumor treatment." (PMID 34862367, 2021). "Pharmacologic inhibition of EZH2, CUL-4A, or the proteasome can increase the steady-state level of DLC1 protein, whose tumor suppressor activity is further increased by AKT and/or SRC kinase inhibitors, which reverse the direct phosphorylation of DLC1 by these kinases." (PMID 34862367, 2021). "Remarkably, most of the reductions in anchorage-independent growth and xenograft tumor growth induced by the combination were found to require DLC1 expression, strongly implying that DLC1 protein makes a critical contribution to the growth inhibition observed with the three-drug combination." (PMID 34862367, 2021). "Silencing of genes involved in cell adhesion may lead to tumor aggressiveness and tumor progression, as was shown for CD97, CTNNA1, DLC1, and HAPLN2 genes in which hypermethylation was associated with poorer survival of patients with ovarian cancer." (PMID 33921911, 2021). "It is possible, that DLC1 may be a signaling partner of p114RhoGEF in some processes as DLC1 was reported to stabilize cell-cell junctions in cultured tumor cells." (PMID 33842485, 2021). "Loss of 8p involving the DLC1, CCDC25, ELP3, PROSC, SORBS3, SH2D4A genes associated with poor outcomes for HCC; in vitro and in vivo analysis indicated that the PROCS, SH2D4A and SORBS3 genes have tumor-suppressive activities and the DLC1 gene is a known tumor suppressor gene." (PMID 34103027, 2021). "In addition, PS binding contributes to the interaction of DLC1-START with Caveolin-1 and PLCD1, and to the tumor suppressor functions of DLC1 that are RhoGAP-independent." (PMID 34727930, 2021). "Interestingly, in this research, two tumor suppressors (DLC1 and HLF) were both found to be closely correlated with AURKB and AURKB-associated differentially expressed miRNAs and hypermethylation." (PMID 33612479, 2021). "Moreover, DLC1, a closely related protein to StarD13 and a well-established tumor suppressor, which inhibits proliferation and induces apoptosis, has also been shown to positively regulate cell migration." (PMID 32900380, 2020). "Dlc1, a tumor suppressing gene, also contributes to the development of placental vasculature." (PMID 33171905, 2020). "DLC1 is a potential tumor suppressor in various cancer types." (PMID 33614496, 2020). "Canine DLC1 is a critical tumor suppressor gene in many types of cancer." (PMID 32051475, 2020). "Finally, xenograft tumour models were used to demonstrate that curcumin restored DLC1 expression by inhibiting EZH2 and also inhibited the growth and promoted the apoptosis of TNBC cells." (PMID 32725802, 2020). "We next tested the effect of expressing the human tumour suppressor DLC1 tagged with Myc." (PMID 29545526, 2018). "DLC1 has been shown to act as a tumor suppressor in a number of experimental cancer models." (PMID 30278072, 2018). "DLC1 is primarily involved in regulating the Rho GTPases (RhoA and Cdc42), which are involved in cancer-related signalling and are closely related to the occurrence and development of tumours." (PMID 29212270, 2017). "Apoptosis induced by resveratrol might be resulted from deacetylation and dephosphorylation of FoxOs, up-regulation of DLC1 and interaction between SIRT1 and DLC1, and dephosphorylation of DLC1 in spontaneous neoplasms of the fish." (PMID 28903430, 2017). "DLC1 is a tumor suppressor and its expression is lost or downregulated in multiple common cancers." (PMID 28881822, 2017). "Deleted in liver cancer 1 (DLC1) is a Rho GAP that is downregulated in various tumor types." (PMID 29036929, 2017). "DLC-1 appeared to also play as a tumor suppressor gene in HCC." (PMID 26846339, 2016).
tumor (continued). "Dlc1 tumour suppressor activity has been attributed to RhoGap dependent and independent activities." (PMID 26977077, 2016). "And re-expression of DLC-1 in cancer cells regulates the structure of actin cytoskeleton and focal adhesions and significantly inhibits cell growth, colony formation and invasion capacity, supporting its role as a tumor suppressor." (PMID 26846339, 2016). "Since almost one-half of the HCC cases had DLC1 copy number changes, this mechanism may be a major factor driving the reduced expression of DLC1 in this tumor type." (PMID 27174913, 2016). "In addition, the prognostic value of DLC1 expression within the tumor tissues was assessed by Cox regression and Kaplan-Meier analysis." (PMID 26846339, 2016). "Chromosome 8p is already known to contain many tumor suppressors, such as DLC1 and FGL1." (PMID 27391266, 2016). "Overexpression of DLC1 inhibits several biological parameters of neoplastic growth, and inactivation of endogenous DLC1 can, in conjunction with other genetic and/or epigenetic changes, lead to cell transformation and tumor formation." (PMID 27174913, 2016). "This also suggests that Dlc1 haploinsufficiency may contribute to tumor progression by disrupting epithelial polarity along with oncogene activation." (PMID 26353792, 2015). "In addition, a series of tumor suppressors including deleted in liver cancer 1 (DLC-1), INK4a and RB, were revealed to be closely correlated to Cav-1 status." (PMID 26431273, 2015). "The DLC1 SNP (rs561681) fits a recessive model, complying with the tumor suppressive role of DLC1." (PMID 25425654, 2014). "In conclusion, in the present study, DLC1 was found to be abundantly present in the environment of the FL variant of HCC, which is rich in fibrous components; furthermore, the FL variant is considered to be a slowly proliferating tumor." (PMID 25013499, 2014). "Thus, localization of DLC1 in the tumor stroma or tumor capsule functions as an inhibitor of the extracellular matrix degradation, which prevents the spreading of cancer cells." (PMID 25013499, 2014). "The migration and proliferation of some tumor cells are reported to be inhibited by DLC1." (PMID 24587289, 2014). "Other studies also confirm the role of DLC1 as a tumor suppressor." (PMID 24627003, 2014). "Cav1 may thus promote the function/activity of DLC1 as a tumor suppressor via direct interaction through a bona fide Cav1-binding motif identified in DLC1." (PMID 23592983, 2013). "A new candidate tumor suppressor gene, DLC-1, was first identified as a rat p122RhoGAP homolog." (PMID 23509688, 2013). "It has been demonstrated that subcellular locations of DLC1 protein determines different manifestations of its antioncogenic action; in cytoplasm DLC1 functions as an inhibitor of tumor cell proliferation and migration, whereas in the nucleus it acts as an inducer of apoptosis." (PMID 22580498, 2012). "The LOH analysis revealed no significant loss at the Dlc1 locus in the majority of tumours; however, we have found microsatellite size alteration for the D8Mit293 marker in one tumour as well as the corresponding cell line DNA." (PMID 22792269, 2012). "Interestingly, treatment with 5 AzaC increased the expression of Dlc1 isoform 2 as compared to the control tumour cell lines (Figure-4C/iii & E)." (PMID 22792269, 2012). "There may well be other tumour suppressor genes, such as DLC1, located on 8p but these appear to be inactivated by alternative mechanisms, including methylation." (PMID 18840272, 2008). "Results showed that DLC-1 might be a NPC-related tumour suppressor gene affected by aberrant promoter methylation and gene deletion." (PMID 17199893, 2007). "Several candidate tumor suppressor genes have been identified from 8p including DLC-1 (8p21.3-22), FEZ1 (8p22), liver-related putative tumor suppressor (LTPS) gene (8p23), PCM1(encoding a centrosomal protein) and DUSP4/MKP-2 (encoding a MAP kinase phosphatase)." (PMID 17784942, 2007).